MELK (maternal embryonic leucine zipper kinase)
Diseases named in the same sentence as MELK in open-access papers (continued):
Sharing a sentence is not in itself a finding about the gene and the disease.
glioblastoma (34 papers, 2012 to 2026). The most malignant astrocytic tumor (WHO grade IV). "MELK induces carcinogenesis effects and is tightly associated with extended survival and accelerated proliferation of CSCs in various tumors, including glioblastoma and BC." (PMID 38701411, 2024). "MELK overexpression is associated with tumor aggressiveness and poor outcomes in numerous other cancer types, including glioblastoma, astrocytoma, and prostate cancer." (PMID 34094915, 2021). "Additionally, MELK has previously been associated with stem cell maintenance in neural stem cells in mouse development and glioblastoma stem cells and metastasis in lung cancer, esophageal cancer, oral cancer, and even triple-negative breast cancer." (PMID 40076867, 2025). "Nonetheless, EZH2 and MELK cooperate in glioblastoma and medulloblastoma to promote cell proliferation and this interplay offers a potential combination therapeutic strategy." (PMID 38183103, 2024). "In glioblastoma, poorer overall survival was noted among patients with higher expression levels of MELK and EZH2." (PMID 38183103, 2024). "EZH2 interacts with maternal embryonic leucine-zipper kinases (MELK) in glioblastoma and medulloblastoma." (PMID 38183103, 2024). "Similar to glioblastoma, medulloblastoma patients had poor overall survival with increased MELK expression postoperatively." (PMID 38183103, 2024). "In glioblastoma stem cells, FOXM1 is phosphorylated by and associates with maternal embryonic leucine-zipper kinase (MELK), and both events are necessary for a MELK–FOXM1 protein complex to bind the EZH2 promoter and stimulate its transcription." (PMID 37686402, 2023). "Recent studies indicated that MELK was highly expressed in several human cancers, including breast cancer, prostate cancer, gastric cancer, liver cancer, glioblastoma multiforme, and lung cancer." (PMID 35693941, 2022). "Compared with normal brain tissues, MELK mRNA expression is upregulated in glioblastoma and this expression gradually increases with greater tumor grades." (PMID 33520717, 2020). "In fact, research in glioblastoma has demonstrated that silencing MELK induces G1/S cell cycle arrest in U87 cells, which is accompanied by a senescence-like phenotype." (PMID 28235006, 2017). "Our observations correlate well with the cytoskeletal changes resulting from MELK knockdown in gastric cancer and glioblastoma cells, and from OTS167 treatment in non small-cell lung cancer." (PMID 28235006, 2017). "Several substrates for MELK have been reported; for example, in glioblastoma stem cells, MELK was found to phosphorylate FOXM1, a crucial transcription factor and a master regulator of mitosis in cancer stem cells." (PMID 25365263, 2014). "Our fundings provide mechanistic insights into glioblastoma pathogenesis and suggest that targeting the MELK-NS pathway may be a potential therapeutic strategy for high-grade gliomas." (PMID 41605804, 2026). "In this study, we identified NS as a novel MELK substrate in glioblastoma U87MG cells." (PMID 41605804, 2026). "MELK is a serine/threonine kinase with a reported role in driving growth in glioblastoma." (PMID 40378113, 2025). "Interestingly, MELK has also emerged as a potential target in cancer research as its expression is significantly elevated in many different tumors, such as glioblastoma, melanoma, breast, prostate, and renal cancer." (PMID 37175795, 2023). "Recent studies also showed that MELK is overexpressed in other types of cancers, such as brain cancer, colon cancer, glioblastoma, and melanoma, and high levels of MELK are correlated with tumor grade, poor prognosis, radioresistance, and recurrence in multiple cancers." (PMID 37377604, 2023).
glioblastoma (continued). "Besides, MELK is also abundantly expressed in glioblastoma multiforme (GBM) and is essential for the proliferation of cancer cells and cancer stem cells." (PMID 32047721, 2020). "However, one previous study in glioblastoma has already hinted at the possibility of differential functions for nuclear and cytoplasmic MELK." (PMID 29437778, 2018). "MELK, a candidate oncogene, is highly expressed in glioblastomas and contributes to tumor growth." (PMID 26468983, 2015). "AML is a clonal disease derived from the hematopoietic stem cells; therefore similar to glioblastoma stem cells, we speculated that MELK-dependent mechanisms might play an important role in leukemia stem-cell survival and proliferation." (PMID 25365263, 2014). "In a recent study, the expression of MELK was found up-regulated in glioblastoma tissue." (PMID 23998913, 2013). "Some specific pathways containing MELK have been identified in glioblastoma multiforme (GBM), such as the c-JUN/MELK and MELK/PRC1 cascades, which support the survival of cancer stem cells (CSCs)." (PMID 31861475, 2019). "In glioblastoma (GBM), mRNA and protein expression of MELK is highly unregulated, and inversely correlates to patient post-surgical survival." (PMID 25852826, 2015). "Consistently, MELK inhibition by OTS-167 treatment significantly suppresses the proliferation and neurosphere formation in glioblastoma stem cells, in which MELK expression is enriched." (PMID 38701411, 2024). "As the MELK gene is discovered to be responsible for Glioblastoma multiforme (GBM), OTSSP167, a MELK inhibitor recently in clinical trial phase I/II, has been synthesized for cancer treatment through MELK inhibition." (PMID 37231064, 2023). "Previous studies suggested contribution of MELK in cancer stem cells due to its high level of expression in cancer stem cell populations (ex, CD133-positive glioblastoma cells)." (PMID 23283305, 2012). "Since both HDAC6 and HDAC4 have been shown to facilitate DNA damage repair in glioblastoma, the synthetic interaction between HDAC4 and HDAC6 with MELK could indicate a role for MELK in DNA damage as well." (PMID 34550356, 2021). "A strong correlation between MELK and STMN1 expressions was observed (r = 0.741, p < 0.0001) in glioblastoma (GBM) samples." (PMID 26973435, 2016). "Interestingly, the level of expression of MELK correlates with the malignancy grade in human astrocytomas: MELK was found to be highly expressed in highly invasive glioblastoma multiforme as opposed to the benign pilocytic astrocytoma." (PMID 23998913, 2013).
glioma (34 papers, 2013 to 2026). A benign or malignant brain and spinal cord tumor that arises from glial cells (astrocytes, oligodendrocytes, ependymal cells). "MELK (maternal embryonic leucine zipper kinase) was elevated in glioma tissues and associated with poorer survival." (PMID 38460058, 2024). "Then, ROC curve analysis showed that the AUC values of MELK at 1, 3, and 5 years were all >0.7, indicating that MELK can serve as a diagnostic biomarker for survival of patients with glioma." (PMID 36353126, 2022). "Our study investigated the prognostic role of MELK in patients with glioma, and the results of both the Kaplan–Meier survival analysis and stratified survival analysis demonstrated that high expression of MELK was associated with poor survival." (PMID 36353126, 2022). "Further, survival analysis was performed to analyze association of MELK/EZH2/NF-κB with prognosis of glioma patients." (PMID 31380279, 2019). "Clinically, we observe that the proportion of MELK/EZH2/NF-κB complex is elevated in high-grade gliomas, which is associated with poor prognosis in patients and correlates negatively with survival." (PMID 31380279, 2019). "MELK has recently attracted considerable interest in cancer biology due to its aberrant overexpression in various malignancies, including glioma, breast, lung, colorectal, gastric, and hematological cancers." (PMID 41594935, 2026). "Some studies have elucidated the anti-FOXM1 activity of MELK and proteasome inhibitors as well as natural products on glioma." (PMID 37821870, 2023). "The relationship between MELK expression and clinicopathologic features of patients with glioma was analyzed in CGGA and TCGA databases." (PMID 36353126, 2022). "According to the median value of MELK mRNA, patients with glioma were divided into high- and low-MELK expression groups." (PMID 36353126, 2022). "Single-sample gene set enrichment analysis (ssGSEA) and CIBERSORT were used to explore the relationship between MELK expression and immune cell infiltration in the microenvironment of gliomas." (PMID 36353126, 2022). "Differentially expressed genes (DEGs) between high- and low-MELK expression groups in gliomas were screened out, and the signaling pathways enriched by DEGs were identified via the gene set enrichment analysis (GSEA)." (PMID 36353126, 2022). "Then, we performed stratified analysis to further explore the role of MELK in glioma, and the results showed that patients in IDH wild type and 1p19q non-codeletion subgroups demonstrated a significantly elevated expression level of MELK." (PMID 36353126, 2022). "In this study, we found that the expression of MELK was significantly upregulated in gliomas, and an elevated MELK level was correlated with poor molecular subtypes, higher WHO grade, and increased histological malignancy." (PMID 36353126, 2022). "The relationship between MELK expression and immune cell infiltration in the microenvironment of gliomas was investigated by ssGSEA and CIBERSORT." (PMID 36353126, 2022). "The glioma RNA-seq data from TCGA dataset was analyzed to screen out the DEGs between high- and low-MELK expression groups using the limma package in R software." (PMID 36353126, 2022). "In our study, we found that the expression level of MELK in glioma tumor tissues was apparently upregulated compared with normal brain tissues." (PMID 36353126, 2022). "Correlation between MELK expression detected by immunohistochemistry and clinicopathologic parameters in patients with glioma (n = 105)." (PMID 36353126, 2022). "Univariate Cox analysis revealed that MELK expression (HR = 1.657; 95% CI = 1.537–1.787; P < 0.001), PRS type, grade, and age were all high-risk factors in the overall survival of glioma, and IDH mutation and 1p19q codeletion were both low-risk factors." (PMID 36353126, 2022). "The key mitotic genes essential for proliferation of glioma stem cells were also regulated by FOXM1 phosphorylation in an MELK-dependent manner." (PMID 36353126, 2022).
glioma (continued). "Collectively, our study provides insights into recognizing the vital value of MELK in prognosis and immunology of glioma." (PMID 36353126, 2022). "The patients with recurrent and secondary gliomas had markedly higher MELK expression than patients with primary glioma." (PMID 36353126, 2022). "The expression of MELK was analyzed in GEO datasets, and the results demonstrated that the expression of MELK was markedly higher in glioma than in normal brain tissues." (PMID 36353126, 2022). "The results indicated that the expression level of MELK was the chief factor for predicting outcomes of patients with glioma." (PMID 36353126, 2022). "Patients with lower histologic expression of MELK/EZH2/NF-KB were less likely to succumb to glioma compared with medium or high expression." (PMID 31380279, 2019). "In the current study, we demonstrate that MELK/EZH2/NF-κB signaling, activated in human high-grade gliomas, represents a key functional hallmark of GSCs and results in the poor prognosis of GBM patients." (PMID 31380279, 2019). "FOXM1 is a master transcription factor that regulates mitotic progression of different types of cancer cells and forms a protein complex with MELK in glioma stem-like cells, leading to phosphorylation and activation of FOXM1 in a MELK kinase-dependent manner." (PMID 26973435, 2016). "At first, we investigated FOXM1 activity because FOXM1 was identified as an important substrate of MELK in glioma stem cells and its activity was attenuated by OTS167 in acute myeloid leukemia cells." (PMID 26871945, 2016). "The correlation between MELK expression and FOXM1 expression in AML patients is consistent with the previously reported association between the two proteins in glioma cells." (PMID 25365263, 2014). "Previous studies have demonstrated that MELK is not only crucial for the development of breast and liver cancers, but also contributes to radio- and chemoresistance in patients with hepatocellular carcinoma and glioma." (PMID 40709174, 2025). "Both MELK and FBXO5 are heavily associated with cancer in general and glioma in particular." (PMID 40378113, 2025). "The previous studies revealed that MELK plays an important role in glioma stem cell proliferation." (PMID 36353126, 2022). "In addition, a nomogram model was constructed based on the clinical information and MELK expression, and the results revealed that the MELK expression was the chief factor for predicting the prognosis of patients with glioma." (PMID 36353126, 2022). "Our research found that the expression levels of six immune checkpoint inhibitors (B7-H3, CTLA4, LAG3, PD-1, PD-L1, and TIM3) were increased with the increase in MELK expression, and significant positive correlations have been found between MELK and these immune checkpoints in glioma." (PMID 36353126, 2022). "More importantly, the immune infiltration analysis revealed that MELK was involved in immune cell infiltration and might mediate the suppressive immune microenvironment of glioma." (PMID 36353126, 2022). "Furthermore, the CCLE database was employed to evaluate MELK expression in different kinds of tumor cell lines, and glioma cell lines showed the highest level of MELK expression." (PMID 36353126, 2022). "In conclusion, MELK acts as an independent prognostic marker of glioma and could predict adverse survival for patients with glioma." (PMID 36353126, 2022). "Finally, immunohistochemistry analysis validated our findings that high expression of MELK relates to increased malignancy and poor prognosis of glioma." (PMID 36353126, 2022). "Moreover, MELK was identified as an independent prognostic factor for patients with glioma through univariate and multivariate Cox regression analyses." (PMID 36353126, 2022).
glioma (continued). "In this study, the expression pattern of MELK in glioma and its relationship with clinicopathologic characteristics and prognosis were identified by analyzing the Chinese Glioma Genome Atlas (CGGA), The Cancer Genome Atlas (TCGA), and Gene Expression Omnibus (GEO) databases." (PMID 36353126, 2022). "Our findings identified that MELK could act as an independent prognostic indicator and potential immunotherapy target for glioma." (PMID 36353126, 2022). "Moreover, based on the clinical information and MELK expression, a nomogram model was constructed to predict the prognosis of patients with glioma in the CGGA dataset." (PMID 36353126, 2022). "Moreover, the relationship between MELK expression and immune cell infiltration in the tumor microenvironment of gliomas was explored through single-sample gene set enrichment analysis (ssGSEA) and CIBERSORT." (PMID 36353126, 2022). "Stratified analysis, Cox regression analysis, and nomogram model revealed that high expression of MELK predicted poor survival; hence, MELK could serve as an independent prognostic biomarker for glioma." (PMID 36353126, 2022). "ROC curve analysis demonstrated that the AUCs for 1, 3, and 5 years were 0.734, 0.698, and 0.707, respectively, which also revealed that MELK might serve as a prognostic indicator for gliomas." (PMID 36353126, 2022). "We first demonstrated that MELK could be a potential immunotherapy target for the treatment of patients with glioma and serve as an independent prognostic indicator for gliomas." (PMID 36353126, 2022). "Finally, immunohistochemistry was performed to validate MELK expression and its relationship with clinicopathologic characteristics and prognosis in patients with glioma." (PMID 36353126, 2022). "Multivariate Cox analysis showed that MELK expression (HR = 1.276; 95% CI = 1.168–1.395; P < 0.001) was independently related to overall survival of patients with glioma, which indicated that MELK could act as an independent prognostic indicator for glioma." (PMID 36353126, 2022). "On the whole, the high expression of MELK indicates a poor prognosis in patients with glioma." (PMID 36353126, 2022). "Moreover, the Kaplan–Meier analysis showed that the survival of patients with glioma in the high-MELK expression group was obviously poorer than that in the low-MELK expression group (HR = 2.38, 95% CI = 1.47–3.87, P <v 0.001)." (PMID 36353126, 2022). "We speculate that our study on MELK may provide a new sight to assist clinical treatment of glioma through immunotherapy." (PMID 36353126, 2022). "Furthermore, the effect of MELK expression on the prognosis of patients with glioma was investigated by stratification analysis." (PMID 36353126, 2022). "Additionally, in recurrent high-grade gliomas, cells where MELK is highly expressed accumulated, and they were incapable of response to conventional treatments." (PMID 32391256, 2020). "Additionally, the impacts of knockdown and inhibitors on tumor burden in our work demonstrate a role of targeted therapy for glioma, which is in agreement with the previous reports aimed to alter activity of MELK/EZH2/NF-κB axis." (PMID 31380279, 2019). "In addition, blocking MELK upregulation in radiation-treated glioma stem cells (GSCs) with shRNA-mediated silencing, and inhibition of MELK with a small molecule kinase inhibitor C1 resulted in increased cellular apoptosis." (PMID 25852826, 2015). "In addition, the expression levels of MELK in patients with primary, recurrent, and secondary gliomas were also analyzed, and statistics showed that MELK expression in patients recurrent and secondary gliomas was markedly upregulated compared with that in patients with primary glioma." (PMID 36353126, 2022).